KRAS (KRas proto-oncogene, GTPase)
Diseases named in the same sentence as KRAS in open-access papers (continued):
Sharing a sentence is not in itself a finding about the gene and the disease.
tumor (continued). "At early checkpoints of PDAC evolution, KRAS-deregulated activity is strictly essential for PanIN progression, an effect that is observed also during late stage of tumor evolution, where neoplastic cells seem to undergo apoptosis upon KRAS oncogene inactivation." (PMID 28895920, 2017). "KRAS gene at 12p12 has long been studied as a crucial oncogene, and tumor cells with wild‐type KRAS may benefit from anti‐EGFR therapy." (PMID 28504856, 2017). "However, it has been identified that miR143 suppresses tumor cell growth and migration, silencing the KRAS (V-Ki-ras2 Kirsten rat sarcoma viral oncogene homolog) gene, and adjusting glucose metabolism via the miR143/HK2 axis." (PMID 29258429, 2017). "Furthermore, in xenograft mouse models, RT11-i sensitized cetuximab-resistant, KRasG13D mutant colorectal LoVo tumours to cetuximab by inhibiting the bypass oncogenic KRas mutant signalling." (PMID 28489072, 2017). "The authors found a much higher frequency of KRAS mutations (codon 12 and 13) in the serum, provided that the tumor was KRAS mutated, 76% as opposed to 30% in this study." (PMID 28378527, 2017). "The blood-based NGS assays did not detect 14 KRAS variants (61%) that were present in the tumor tissue." (PMID 29137355, 2017). "Recent studies have demonstrated that blocking MYC function may be sufficient to stop tumor growth and induce tumor regression in the well-characterized LSL KRAS G12D mouse models of NSCLC and PDAC." (PMID 28152508, 2017). "In conclusion, this meta-analysis found that ICIs as a salvage therapy improved OS over that with docetaxel in advanced NSCLC patients with KRAS mutation, but not in those with KRAS wild-type tumor." (PMID 28525386, 2017). "Moreover, suppression of TET1 expression was reported to be associated with facilitated cell invasion and metastasis and even to play a critical role in KRAS-induced tumour transformation." (PMID 28228863, 2017). "In this sample, there were three copies of the KRAS gene, and a tumour cell content of 65%." (PMID 28315634, 2017). "However, GFAP levels were dramatically decreased in the tumor cells from c-Myc/kRas/Akt3 combination mice." (PMID 26993778, 2016). "AT7519, a CDK1/2/4/5/9 inhibitor, showed the greatest selectivity for KRAS mutant tumour cells." (PMID 26881434, 2016). "Since RAS is a crucial signaling pathway known to regulate the homeostatic proliferation of normal cells, it was important for us to evaluate if the CXCR2 antagonists provide a selective growth disadvantage to mutant KRAS-bearing tumor cells versus normal cells." (PMID 26771140, 2016). "Mutation in KRAS leads to the uncontrolled activation of downstream intracellular signaling pathways such as the RAF/MEK/extracellular signal regulated kinase (ERK) and AKT contributing to tumor cell proliferation and survival." (PMID 27200288, 2016). "None of the tumor tissue samples of all 46 patients showed evidence of mutations in the cetuximab-interacting EGFR ectodomain or KRAS/NRAS." (PMID 27119512, 2016). "Evidence at that time from small single-arm studies in chemorefractory mCRC suggested that responses to treatment with cetuximab were confined to patients whose tumours did not harbour KRAS codon 12 or 13 (exon 2) mutations." (PMID 26766738, 2016).
tumor (continued). "Interestingly, the pattern of increased expression of this module of inflammatory cytokines was maintained in the group of KRAS mutant tumours, which by definition are resistant to treatment." (PMID 27708224, 2016). "The mean tumor weight was higher (NS) in the orthotopic implants of E6-E7-st/KRAS-shCXCR2 cells." (PMID 26771140, 2016). "Furthermore, to confirm that PTD-RBD-VIF inhibited the expression of mutant KRAS in vivo, representative tumor tissues were digested with collagenase and hyaluronidase and cells were disrupted and analyzed by western blotting." (PMID 27322423, 2016). "Because of the low percentage of KRAS-mutated tumours, no further statistical analyses were performed." (PMID 26844548, 2016). "EGFR expression was analysed in tumours from three independent patient cohorts; cohort 1 (n = 533), cohort 2 (n = 259) and cohort 3 (n = 310), previously analysed for immunohistochemical PODXL expression and KRAS and BRAF mutations (cohort 1 and 3)." (PMID 27160084, 2016). "Alternatively, some of the differences in the distribution of KRAS substitutions might be attributed to differences in natural selection, due to differences in KRAS protein function within the different tumor types." (PMID 26902163, 2016). "In a murine tumor cell line without PC-bearing cells, inhibition of the mutated KRAS signaling pathway lead to re-development of PC." (PMID 27783689, 2016). "In this study, we used the Taiwan Cancer Registry (TCR) and NHI databases concomitantly to evaluate the association between a primary tumor site and the clinical benefits of cetuximab in patients with KRAS wild-type (exon 2 nonmutant) metastatic CRC." (PMID 27221731, 2016). "About 20% of patients with KRAS exon 2 non-mutated tumours harboured one of the extended RAS mutations." (PMID 27999270, 2016). "Indeed, activating mutations in KRAS, NRAS and BRAF genes are found in up to 60% of CRCs and are acquired at an early premalignant stage consistent with a role in tumor initiation and/or progression." (PMID 27582544, 2016). "However, only approximately 40 % of CRC patients with tumours wild-type for KRAS, NRAS and BRAF benefit from such therapy, and patients who initially respond eventually become resistant to these drugs." (PMID 27160084, 2016). "Upon correction of the discordant data all tumor blocks showed a homogenous KRAS status." (PMID 27064574, 2016). "Thus, differences in mutational biases have the potential to contribute to the observed variation found between tumor types in the distribution of KRAS driver substitutions." (PMID 26902163, 2016). "We show that within each tumor type selection favors certain KRAS driver substitutions over others." (PMID 26902163, 2016). "A multivariate Cox analysis for the 200 CRC showed that the 6-GPS remained significantly associated with patients' RFS (HR=3.05; 95% CI: 1.66–5.60; P-value=3.36E-04), after adjusting for tumor stage, gender, age, tumor location, mismatch repair status and gene mutation (BRAF and KRAS)." (PMID 27429074, 2016).
tumor (continued). "At the same time within each tumor type the KRAS driver substitution that was identified as being favored only in that tumor type (c.34G > T for LUAD, and c.34G > C for PAAD) showed a significant association with tumor stage (P = 0.01 and 0.03, for LUAD and PAAD respectively)." (PMID 26902163, 2016). "From the cases in which a tumor carried a KRAS substitution we could calculate the relative frequencies at which each of the twelve possible codon 12 and 13 KRAS driver substitutions occurred within the different tumor types." (PMID 26902163, 2016). "We confirm here that microinjection of KRASG12D mRNA, a tumor-inducing KRAS mutant, results in the formation of the ITLSs that we have previously shown to exhibit classic hallmarks of tumors, including histopathology, increased proliferation, lack of differentiation, attraction of vasculature, etc.." (PMID 26988909, 2016). "By accounting for the effects of mutation on the distribution of KRAS driver substitutions, we could identify specific KRAS driver substitutions that are more favored by selection in specific tumor types." (PMID 26902163, 2016). "Mechanistically, KRAS K147 is identified as a novel SIRT2-specific deacetylation target by mass spectrometry, whereas its acetylation status directly regulates KRAS activity, ultimately exerting an impact on cellular behavior as revealed by cell proliferation, colony formation, and tumor growth." (PMID 27637077, 2016). "Of the 37 evaluable patients, one demonstrated a false negative KRAS codon 12 mutation and an additional two patients did not have sufficient primary tumor nucleic acid isolation; these patients were removed from subsequent analyses." (PMID 26980732, 2016). "Overall, 38% of patients had KRAS exon 2 mutations, and 10% had RAS mutations beyond KRAS exon 2 (KRAS exon 3 and 4 mutations each in 3% of tumours; NRAS exon 2 and 3 mutations each in 2% of tumours; no tumour was found to carry an NRAS exon 4 mutation)." (PMID 27764839, 2016). "KRAS mutation was also frequent in tumours without family history of malignancies, although this tendency was not statistically significant (p = 0.07, data not shown)." (PMID 26298837, 2016). "Only patients with a KRAS wild-type tumor may benefit from additional (third-line) treatment with an epidermal growth factor receptor (EGFR)-targeted monoclonal antibody (panitumumab or cetuximab)." (PMID 27782851, 2016). "Of the ten tumours with higher ZEB1, five (50%) had KRAS mutations." (PMID 27456471, 2016). "This agreement indicates that KRAS mutations at codon 12 or GNAS mutations at codon 201 could play a key role as the driver of carcinogenesis, providing a selective advantage in tumor formation associated with these IPMNs." (PMID 27095449, 2016). "Furthermore, Sirt2-/--KrasG12D serial lung sections showed nests of tumor cells exhibiting increased in vivo pERK and Ki-67 staining, implying increased KRAS activity and tumorigenicity in the lungs when Sirt2 is deleted." (PMID 27637077, 2016). "Prior to performing KRAS mutation detection on any plasma derived DNA, the corresponding matched FFPE tissue was screened using the therascreen KRAS RGQ PCR kit to identify patients with mutation positive tumours (n = 10/20; data not shown)." (PMID 26918901, 2016). "The observed paradoxical effect of zoledronic acid on VEGF in wild type KRAS expessing NSCLC tumor and its consequences on improved vascularization/vessel stabilization may easily follow similar biological trends." (PMID 27780929, 2016). "In addition, we constructed tumor xenografts in mice and showed that miR-16 inhibits tumor growth, partially by negatively regulating KRAS expression." (PMID 27857191, 2016).
tumor (continued). "Even though the tumor biology and prognosis of patients with concomitant KRAS and BRAF mutations have been still uncertain, previous research suggests that these concomitant mutations are associated with tumor progression such as lymph node metastasis and higher T stage." (PMID 26991109, 2016). "Overall survival (median 30.0 months (95% CI 23–NA) vs 7.0 months (95% CI 5.0–37.0)) and PFS (median 12.0 months (95% CI 8.0–20.0) vs 7.0 months (95% CI 4.0–18.0)) were also longer among patients with KRAS exon 2 wild-type tumours compared with those with KRAS exon 2 mutant tumours." (PMID 26766738, 2016). "Taking into account the regulatory role of SIRT2, we present here evidence to further establish the tumor suppressor role of SIRT2 in a KRAS-specific context by proposing that the acetylation status of K147 may direct activity and transformative properties." (PMID 27637077, 2016). "Furthermore, re-expression of miR-96 and 217 suppressed KRAS activity and resulted in reduced tumor migration and invasion, suggesting their role as tumor suppressors." (PMID 27322337, 2016). "Except for one tumor, tumors having both EGFR and KRAS mutations were moderately differentiated." (PMID 26992209, 2016). "We observe that stromal cells approximately double the number of tumor cell signaling nodes regulated by oncogenic KRAS, suggesting both cell-autonomous (internal) and reciprocal (external) stimuli should be considered when defining aberrant oncogenic signaling states." (PMID 27087446, 2016). "Indeed, our studies demonstrate that combined inhibition of MEK and CKD4/6 is synergistic in vitro in a variety of KRAS mutant CRC cell lines and yields tumor regression in vivo in cell line xenografts and PDXs of KRAS mutant CRC." (PMID 27167191, 2016). "We report an inexpensive, rapid multiplex allele-specific qPCR method detecting the 7 most clinically relevant KRAS somatic mutations with concomitant amplification of non-mutated KRAS in tumor cells and tissues from CRC patients." (PMID 27632281, 2016). "In our study, the percentage of KRAS G12V in tumor-derived DNA was 36.83% (n = 10, median)." (PMID 27043547, 2016). "Both miR-193b and miR-365a could acted as a tumor suppressor in the epidermis by directly targeting KRAS oncogene." (PMID 26646588, 2016). "Two AIO KRK studies (0104 and 0306) demonstrated that in populations with either KRAS wild-type (codon 12/13) or expanded RAS, a left primary tumor site was associated with long PFS and OS in untreated metastatic CRC patients who received cetuximab-containing regimens." (PMID 27221731, 2016). "Taken together, these lines of evidence strongly support the theory that CXCR2 signaling might play an important role in KRAS-induced tumor cell-autonomous growth by directly contributing to its intracellular signaling during PDAC development and progression." (PMID 26771140, 2016). "Moreover, tumor cells with a mutant KRAS are more radiation-resistant than are cells with the wild type of KRAS48." (PMID 26884312, 2016). "For single gene or tumor phenotype biomarker, microsatellite instability (MSI) high is a validated prognostic biomarker in early stage colorectal cancer while the prognostic value of BRAF or KRAS mutation depends on microsatellite status and tumor location." (PMID 27623752, 2016).
tumor (continued). "As previously reported, the majority of these alterations were located at the hotspot codon 12, the spectrum was concordant with the distribution of KRAS tumor mutation types from ICGC data, suggesting that KRAS mutations in the circulating DNA mainly originate from tumor cells." (PMID 27705932, 2016). "Mutations in KRAS, NRAS, BRAF, and PIK3CA genes were evaluated for association with several pathological parameters: sex, age at diagnosis, anatomical location of primary CRC, tumour grading, AJCC stage of the disease." (PMID 27737711, 2016). "Here, we show that oncogenic KRAS (KRASG12D) also regulates tumor cell signaling via stromal cells." (PMID 27087446, 2016). "Furthermore, experiments using tumor xenografts in mice validated the tumor-suppressive role of miR-16 in CRC tumorigenesis through the targeting of KRAS." (PMID 27857191, 2016). "While KRAS mutations were frequently detected in 46 (41%) out of 112 FAP tumor samples, no sample was BRAF-mutation(+)." (PMID 27563825, 2016). "As a result, we found that reduced NDRG4 mRNA expression was associated with tumor progression, as well as unfavorable outcome independent of patients' clinical features and molecular variables including KRAS, BRAF and PIK3CA mutations and MSI status." (PMID 26515606, 2016). "miR-200c also had an anti-tumor effect by negatively regulating KRAS in a xenograft mouse model." (PMID 26392416, 2015). "Simultaneous activation of the KRAS oncogene together with inactivation of NF1 tumour suppressor could be lethal to cell survival, and hence these two events rarely co-occur (p-value = 0.001)." (PMID 26427375, 2015). "In particular, some CRC PDX models exhibited significant tumor regression, particularly those harboring mutations in KRAS and BRAF with no mutation in PIK3CA." (PMID 26439693, 2015). "Interestingly, we identified focal KRAS amplification in a biopsy of a tumor from a patient that had become resistant to crizotinib treatment." (PMID 25691052, 2015). "There was no indication from the free-text responses that these oncologists were unaware of the contraindication of administering panitumumab simultaneously with oxaliplatin-containing chemotherapy to mCRC patients with tumor KRAS status unknown." (PMID 26491871, 2015). "Furthermore, the discovery of a synthetic lethal interaction between K-Ras oncogenes and CDK4 in a mouse tumour model of NSCLC revealed that KRAS-driven NSCLC is particularly dependent on CDK4." (PMID 25625291, 2015). "Of the 4 patients with mutant KRAS in the primary tumor that were negative for a KRAS mutation in plasma, 3 had previously received chemotherapy." (PMID 26498594, 2015). "The main findings were that KRAS mutation was associated with advanced disease stage, BRAF mutations were mainly found in right colon, PIK3CA was associated with poor tumour differentiation, MSI was more commonly seen in lower disease stage, larger and more poorly differentiated tumours." (PMID 25884297, 2015). "To evaluate the effect of blocking redox-dependent reactions with C118 in wild-type KRAS on oncogenic HRASG12V-driven tumorigenesis, we monitored tumor growth of oncogenic HRASG12V-transformed cells upon replacing the endogenous wild-type KRAS protein with the C118S mutant version." (PMID 25902334, 2015).